ZMYM4 (zinc finger MYM-type containing 4)
Description:
Required for regulation of cell morphology and cytoskeletal organization.
Synonyms: KIAA0425; ZNF262; ZNF198L3; MYM; CDIR
Tractability: PROTAC: UniProt records ubiquitination sites on it; ubiquitination databases record sites on it; its protein half-life has been measured.
Gene: Protein-coding gene on chromosome 1 (35,268,667 to 35,422,058, forward strand). Ensembl gene ENSG00000146463.
Subcellular location (Human Protein Atlas): Nucleoplasm; Cytosol; Nucleoli
Gene Ontology:
Molecular function: protein binding; DNA binding; zinc ion binding
Genetic constraint (gnomAD): Loss-of-function variants: 29 observed, 175.57 expected, observed/expected ratio (o/e) 0.17, 90% interval 0.12 to 0.22. The upper end of that interval is the gene's LOEUF score, 0.22, which puts it in group 1 of 6, group 1 being the genes least tolerant of losing a copy. Missense variants: 1,236 observed, 1,847 expected, observed/expected ratio (o/e) 0.67, 90% interval 0.64 to 0.7. Synonymous variants: 573 observed, 639.74 expected, observed/expected ratio (o/e) 0.9, 90% interval 0.84 to 0.96.
Homologues: Orthologues: chimpanzee ZMYM4 (99% identical), macaque ZMYM4 (99% identical), rabbit ZMYM4 (98% identical), pig ZMYM4 (98% identical), dog ZMYM4 (98% identical), mouse Zmym4 (94% identical), rat Zmym4 (94% identical), guinea pig ZMYM4 (89% identical), tropical clawed frog zmym4 (70% identical). Paralogues in human: ZMYM6 (36% identical), ZMYM2 (32% identical), ZMYM3 (31% identical), ZMYM1 (21% identical), QRICH1 (14% identical), ZMYM5 (10% identical), GTF2IRD1 (8% identical), KIAA1958 (7% identical), THAP12 (6% identical), SCAND3 (5% identical), GTF2I (5% identical), ZBED11 (5% identical), and 6 more.
Diseases named in the same sentence as ZMYM4 in open-access papers:
ZMYM4 is named in the same sentence as 15 diseases in open-access papers, as found by Europe PMC text mining. Sharing a sentence is not in itself a finding about the gene and the disease. The quoted sentences say what the papers report.
mental retardation (2 papers, 2011 to 2014). "The other genes are potassium channel tetramerization domain containing 1 (KCTD1), zinc finger, myeloproliferative and mental retardation type 2 (ZMYM2)/zinc finger protein 198 (ZNF198), ZMYM3/ZNF261, ZMYM4/ZNF262 and glutamine-rich protein 1 (QRICH1)." (PMID 22011512, 2011).
Alzheimer disease (1 paper, 2025). A progressive, neurodegenerative disease characterized by loss of function and death of nerve cells in several areas of the brain leading to loss of cognitive function such as memory and language. "ZMYM4 is also down-regulated in Alzheimer’s Disease (GSE1297), Parkinson’s Disease (GSE7621), chronic obstructive pulmonary disease (GSE3320) and large granular lymphocytic leukaemia (GSE10631) in the Disease Signatures from GEO 2014." (PMID 40656995, 2025).
Lynch syndrome (1 paper, 2024). An autosomal dominant hereditary neoplastic syndrome characterized by the development of colorectal carcinoma and a high risk of developing endometrial carcinoma, gastric carcinoma, ovarian carcinoma, renal pelvis carcinoma, and small intestinal carcinoma. "The gene ontologies for list 7- linked CHTOP, ADNP, HLTF, WAPL, ZMYM4, and ZNF146 to Lynch Syndrome." (PMID 39480826, 2024). "We propose that ADNP, CHTOP, HLTF, MTF2, WAPL, and ZMYM4 are novel genes in Lynch Syndrome." (PMID 39480826, 2024).
malignant melanoma (1 paper, 2024). "The ZMYM4-OPRD1 fusion gene has been associated with breast cancer, while ZMYM4 has been associated with colonic and gastric cancers, malignant melanoma, hepatocellular carcinoma and pancreatic carcinomas." (PMID 39480826, 2024).
Obesity (1 paper, 2020). Accumulation of substantial excess body fat. "We identify three genes (PHIP, DGKI, and ZMYM4) newly implicated in obesity, harboring very rare predicted deleterious alleles, with intermediate effects and penetrance between those identified through family or large-population scale efforts." (PMID 32492392, 2020).
cancer (4 papers, 2020 to 2024). A tumor composed of atypical neoplastic, often pleomorphic cells that invade other tissues. "Mutations in ZMYM4 are associated with severe childhood obesity, schizophrenia, heritable substance use disorders, heritable sleep disorders, and cancers." (PMID 37854072, 2023). "Although Zmym4 has been implicated in regulating early brain development and certain cancers, its role in craniofacial development has not previously been described." (PMID 37854072, 2023).
blood disorders (1 paper, 2025). "Furthermore, four genes–UQCRFS1, PTPN6, RALY and ZMYM4–were identified for their associations with traits such as aging, forebrain and nervous system morphology, lung and bone morphology, neurodegenerative diseases and blood disorders." (PMID 40656995, 2025).
ZMYM4 also shares sentences with these, for which no sentence is quoted: cholangiocarcinoma (1 paper); chronic obstructive pulmonary disease (1); intrahepatic cholangiocarcinoma (1); large granular lymphocytic leukaemia (1); lung adenocarcinoma (1); neurodegenerative disease (1); Parkinson disease (1); squamous cell carcinoma (1).